TIMP2 (TIMP metallopeptidase inhibitor 2)
Diseases named in the same sentence as TIMP2 in open-access papers (continued):
Sharing a sentence is not in itself a finding about the gene and the disease.
Sepsis (continued). "Markers of cell-cycle arrest, such as TIMP-2 and IGFBP7, have been identified as potential predictors of sepsis-induced AKI, underscoring the importance of this mechanism in human sepsis." (PMID 40091836, 2025). "The potential of TIMP-2 as a biomarker for SA-AKI was subsequently studied in three groups of 56 male rats (6 controls, 24 sham-operated rats, and 24 rats suffering from sepsis)." (PMID 39001241, 2024). "We found that sepsis enhanced the expression of E‐cadherin, ZO‐1, MMP2, and MMP9 but weakened that of TIMP‐2 and TIMP‐3." (PMID 37525933, 2023). "Hoffmann and collaborators reported elevated levels of matrix metalloproteases and their inhibitors (MMP-9, TIMP-2 and TIMP-1) in severe sepsis, and TIMP-1 was suggested as a useful biomarker in predicting the clinical outcome of patients with severe sepsis." (PMID 37817235, 2023). "In the setting of medical and non-sepsis patients, urinary NGAL had better predictive performance than urinary IL-18, urinary L-FABP, and urinary TIMP-2 × IGFBP-7: 0.3." (PMID 36371256, 2022). "Moreover, we first showed that adding u[TIMP-2]*[IGFBP7] to the clinical risk factor model, alone or combined with renal injury biomarkers, significantly improved the risk classification of AKI progression and AKI progression with death in sepsis, as evidenced by significant NRI and IDI." (PMID 34906098, 2021). "u[TIMP-2]*[IGFBP7], measured at time of AKI diagnosis, predicted both AKI progression and AKI progression with death in the setting of sepsis." (PMID 34906098, 2021). "Currently, NephroCheck, based on urinary [TIMP2]*[IGFBP7], is the only FDA approved test for early detection of AKI, which has a relatively low sensitivity for sepsis patients." (PMID 33204323, 2020). "Urinary [TIMP2]*[IGFBP7] showed a sensitivity of 60% and a specificity of 85% for AKI diagnosis in the patients with sepsis, while urinary miR-376b had a sensitivity of 65% and a specificity of 85%." (PMID 33328388, 2020). "We compared the efficacies of urinary miR-376b and urinary [TIMP2]*[IGFBP7] in the diagnosis of patients with AKI and sepsis." (PMID 33328388, 2020). "The other markers already well studied in ICU patients or sepsis (e.g., KIM-1, IL-18, IGFBP-7, and TIMP-2) should be verified in the AP patients." (PMID 31366007, 2019). "The results indicate that MMP-9, TIMP-2, and TIMP-1 showed the higher sensitivity, specificity, and positive predictive value for sepsis." (PMID 31671729, 2019). "Following this logic, the Limiting AKI Progression in Sepsis trial was designed to evaluate the application of these bundles guided by serial measurements of TIMP-2 × IGFBP7 in patients with sepsis who did not have KDIGO stage 2 or 3 disease AKI at enrollment." (PMID 38462074, 2024). "The [TIMP-2] × [IGFBP-7] test could be useful in patients undergoing major surgery, who are hemodynamically unstable, or have sepsis." (PMID 39001241, 2024). "The results showed that an increase in TIMP2*IGFBP7 4 h after the surgery is a reliable predictor of AKI (sensitivity, 83.9%; specificity, 73.8%), and an increase in MR-proADM is an indication of the potential occurrence and severity of postoperative sepsis." (PMID 39336978, 2024). "Previous studies have reported that [TIMP-2]•[IGFBP7] (the product of TIMP-2 and IGFBP7) has shown significant predictive ability for the progression of AKI (stages 2–3) within 12 h of sample collection in patients with various diseases, including sepsis." (PMID 38702662, 2024). "In the group negative for sepsis, TIMP-2 concentrations were 86.5 (63.9–265.0) ng/ml in plasma and 0.0 (0.0–30.1) ng/ml in peritoneal fluid, respectively." (PMID 33488296, 2021). "Similar to LPS-induced AKI mice, there was a subset of sepsis patients with AKI whose [TIMP2]*[IGFBP7] values were no different from that of patients without AKI." (PMID 33204323, 2020).
Sepsis (continued). "Especially, a significant portion of sepsis patients with AKI had urinary [TIMP2]*[IGFBP7] that was similar to that of sepsis patients without AKI, resulting in the failure of detecting AKI in these patients by using urinary [TIMP2]*[IGFBP7]." (PMID 33204323, 2020). "The mean values of urinary [TIMP2]*[IGFBP7] were significantly higher in the patients with sepsis and AKI than in those without AKI." (PMID 33328388, 2020). "Moreover, compared with urinary [TIMP2]*[IGFBP7], urinary miR-376b even showed a moderately higher sensitivity (65% vs. 60%) for detecting AKI in patients with sepsis." (PMID 33328388, 2020). "Nonetheless, the increase of urinary TIMP2 and IGFBP7 in AKI mainly depends on renal proximal tubule injury, raising the concern that mild tubular injury in septic AKI would reduce the sensitivity of [TIMP2]*[IGFBP7] in early AKI detection in sepsis patients." (PMID 33204323, 2020). "Notably, compared to urinary [TIMP2]*[IGFBP7] or the FDA approved AKI biomarker, miR-452 showed a remarkable merit in the sensitivity of AKI detection in sepsis." (PMID 33204323, 2020). "Sepsis patients with AKI had a significantly bigger value of urinary [TIMP2]*[IGFBP7] than the patients without AKI." (PMID 33204323, 2020). "Interestingly, in severe sepsis, the expression levels of MMP-9, TIMP-1, and TIMP-2 are also significantly elevated." (PMID 31671729, 2019). "To date, the influence of sepsis on TIMP-2 and IGFBP7 expression in critically ill patients is not well defined." (PMID 28884304, 2017). "In our study, urinary [TIMP-2]·[IGFBP7] was an early predictor of AKI in ICU patients regardless of sepsis." (PMID 28884304, 2017). "Taking into account the characteristics of our population, we conducted stepwise logistic regression analysis using as covariates age, sepsis, shock, previous hepatopathy, secondary ARDS, SAPS II, SOFA at admission and the worst value [TIMP-2]·[IGFBP7] for AKI and AKIN ≥ 2 prediction." (PMID 28884304, 2017). "Although plasma NGAL and IL-6 were increased by sepsis, urinary TIMP-2 and NAG were increased not by sepsis, but by the presence of severe AKI." (PMID 25524453, 2014). "A clinical evaluation revealed that urinary TIMP-2 was not inferior to any other biomarker, especially in patients with sepsis." (PMID 25524453, 2014). "Combining u[TIMP-2]*[IGFBP7] with UACR could not further improve the performance both for predicting AKI progression or AKI progression with death in sepsis." (PMID 34906098, 2021). "The sensitivity of urinary miR-452 for AKI detection in sepsis patients reached 87.23%, which was notably higher than the 61.54% achieved by urinary [TIMP2]*[IGFBP7], while the specificity of urinary miR-452 (78.00%) was slightly lower than that of [TIMP2]*[IGFBP7] (87.18%)." (PMID 33204323, 2020). "The combination of [TIMP-2] × [IGFBP7] and PCT with cut-offs of 0.3 and 0.5, respectively, may help in stratifying the risk for AKI, regardless of sepsis." (PMID 32318859, 2020). "In a mouse model of sepsis, TIMP-2 and IGFBP7 were shown to predict the development of AKI, with an area under the receiver operating characteristic curve (AUC) of 0.76 and 0.72, respectively; the result for the [TIMP-2]·[IGFBP7] complex was 0.89 (95% CI, 0.80–0.98)." (PMID 29854781, 2018). "[TIMP-2]·[IGFBP7] index values were dependent on the incidence of AKI but not of sepsis." (PMID 28884304, 2017). "We observed no significant impact of sepsis on urinary TIMP-2, although the authors of a previous report presented a better prediction of AKI by the combination of TIMP-2 and insulin-like growth factor-binding protein-7 (IGFBP-7) in septic subjects than in post-surgery subjects." (PMID 25524453, 2014). "Therefore, urinary TIMP-2 × IGFBP-7 examination may offer additional benefits regarding short-term mortality in the general population of patients visiting the ED, in contrast to patients with sepsis and a high incidence of AKI." (PMID 39811377, 2025).
Sepsis (continued). "Known renal injury markers, such as markers Lcn2 (NGAL), Havcr1 (KIM1), Timp2, Igfbp7, are tubular injury markers and therefore are not indicative of the microvascular response in mouse CLP-sepsis." (PMID 40892345, 2025). "Nevertheless, the sensitivity of TIMP-2 and IGFBP7 for diagnosing AKI in critically ill and sepsis patients remains as high as 0.87, and the negative likelihood ratio is 0.15 (95% CI: 0.04–0.64), indicating a considerable ability to rule out AKI." (PMID 41332898, 2025). "In a murine model of sepsis-induced AKI, systemic CSF2 administration, not TIMP2, attenuates AKI severity and improves mouse survival through promoting alternative macrophage transition." (PMID 38421825, 2023). "In non-AKI patients, individual [TIMP-2]·[IGFBP7] levels were highest in trauma and sepsis patients." (PMID 25866432, 2015). "Univariate logistic regression analysis demonstrated significant associations between renal non-recovery and several factors, including age, sepsis severity, serum lactate level, SCr at enrollment, AKI stage, as well as urinary levels of [TIMP-2]•[IGFBP7] and CCL14 (all with P < 0.05)." (PMID 38702662, 2024). "Urinary TIMP-2 and NAG were elevated in AKI, irrespective of sepsis complication." (PMID 25524453, 2014). "However, urinary TIMP-2 and NAG were not influenced by sepsis." (PMID 25524453, 2014).
melanoma (51 papers, 1999 to 2026). A malignant, usually aggressive tumor composed of atypical, neoplastic melanocytes. "Recently, TIMP-2 has been implicated in the mechanism of resistance to BRAF inhibitors in melanoma cells." (PMID 40869222, 2025). "In another study, transfection of the melanoma cell line M24net with cDNA encoding human TIMP-2 effectively suppressed MPP-1, -2, and -9 activity in a xenograft model of immunodeficient mice." (PMID 39594665, 2024). "Expression profiles of FABP5, IVL, KRT6A, KRT15, KRT16, and TIMP2 provide clues of prognostic implications, which might help us evaluate malignant potential of nevus and underlying carcinogenesis progress from melanocytic nevus to melanoma." (PMID 32934956, 2020). "Further, alterations in the expression profiles of FABP5, IVL, KRT6A, KRT15, KRT16, and TIMP2 were significantly associated with worse prognosis, indicating that these hub genes may participate in the aggressive transformation from a nevus to malignant melanoma." (PMID 32934956, 2020). "Transcription profiles of FABP5, IVL, KRT6A, KRT15, KRT16, and TIMP2 provided clues of prognostic implications, which might help us evaluate malignant potential of nevus and underlying carcinogenesis progress from melanocytic nevus to melanoma." (PMID 32934956, 2020). "The comparison of data obtained with NHKs, NHFs, and CAFs exposed to melanoma-derived SPNs evidenced bFGF, CXCL-16, and TIMP-2 as common features, suggesting a crucial role for melanoma biology." (PMID 40869222, 2025). "In this study, our four novel oncolytic adenoviruses armed to express one or both PADI1 and TIMP2 exhibited varied levels of cytotoxicity against four melanoma cell lines in vitro in a dose-dependent manner." (PMID 36816748, 2023). "TIMP2 is thought to block the Wnt/catenin pathway, which is supposed to inhibit the proliferation of melanoma cells, although the function of TIMP1 on carcinogenesis is less clear." (PMID 36975387, 2023). "A regulator of the extracellular matrix (ECM), tissue inhibitor of metalloprotease type 2 (TIMP2), is overexpressed in regressing parts of melanomas." (PMID 36816748, 2023). "A connection between TIMP-2 and the NF-kB signaling pathway has been established in melanoma cell lines and lung epithelial cells." (PMID 38137108, 2023). "In further support of our findings, previous studies have reported that TIMP2 inhibits Wnt/β‐catenin signaling in melanoma." (PMID 32118353, 2020). "In melanoma B16F10 cell line TIMP-2 overexpression reduced invasion and angiogenic abilities of these cells." (PMID 33023532, 2020). "Results of TIMP-2 revealed that concentration levels of TIMP-2 in CaG5 treated melanoma cells were higher than those in IQG, HEG, or control groups: CON, 54.69 ± 1.54 ng/ml; CaG5, 207.65 ± 41.18 ng/ml (CaG5 vs. CON, p < 0.05); and IQG5, 23.82 ± 30.36 ng/ml." (PMID 30611221, 2019). "The overexpression of TIMP-2 in a highly metastatic melanoma cell line was able to inhibit metastasis." (PMID 28427184, 2017). "In vivo it also downregulates MMP-2 in a human melanoma mouse model, and MMPs-2 and -14 in gallbladder cancer, thereby enhancing the VM-inhibiting activity of TIMP-2." (PMID 29112161, 2017). "It was demonstrated that overexpression of TIMP2 in melanoma cells and cells of other types of cancer inhibits the tumor growth, angiogenesis, tumor invasiveness and metastasis." (PMID 27088717, 2016). "In melanoma cells TIMP-2 over-expression is sufficient to increase NF-κB activity and protect cells from apoptosis." (PMID 26361584, 2015). "Further, TIMP-2 over-expression stimulates proliferation of human osteosarcoma and A549 lung AC cells and protects melanoma cells from apoptosis by modulating the NF-κB pathway." (PMID 25296976, 2014). "In previous studies, TIMP-2 overexpression reduced invasion and angiogenesis, and protected melanoma cells from apoptosis." (PMID 24278338, 2013).
melanoma (continued). "HSA/TIMP-2 was injected every two days in this study, whereas 40 mg/kg HSA/TIMP-2 was injected daily in the B16BL6 melanoma xenograft study." (PMID 22545131, 2012). "Our data suggest that TIMP-2 over-expression is able to protect cells from apoptosis in human melanoma A2058 cells." (PMID 21152266, 2010). "It is consistent with the previous studies that TIMP-2 overexpression protects B16F10 melanoma cells from apoptosis reduced." (PMID 21152266, 2010). "We highlight the roles of the TIMP-2 in modulating the proinflammatory NF-κB pathway in melanoma and lung caner cells." (PMID 21152266, 2010). "TIMP2 can promote apoptosis in an in vivo colorectal cancer model yet can protect B16 melanoma cells from apoptosis." (PMID 16972989, 2006). "TIMP-1 and -3 were abundantly expressed in the cancer and/or stromal cells of grade III and IV melanomas, while TIMP-2 protein was detected also in melanomas representing lower invasive potential." (PMID 10360651, 1999). "However, TIMP‐2 overexpressing clones were found to be more resistant to apoptosis than parental and control melanoma cells, indicating a potential role for TIMP‐2 in cell survival." (PMID 41546170, 2026). "TIMP-2 is a secreted protein widely expressed across various neoplastic tissues including melanoma." (PMID 40869222, 2025). "However, other studies argued for a role in melanoma progression because TIMP-2 was found to be more elevated in cutaneous melanoma compared to nevus." (PMID 40869222, 2025). "Notably, elevated expression of TIMP-2 has been observed in various neoplastic diseases, including lung cancer, prostate cancer, and melanoma." (PMID 39769318, 2024). "In addition, survival curves indicated that six hub genes, including FABP5, IVL, KRT6A, KRT15, KRT16, and TIMP2, were significant prognostic signatures for CM and of significant value to predict transformation from nevi to melanoma." (PMID 32934956, 2020). "For example, elevated expression of TIMP2 suppresses the proliferation of melanoma cells via the Wnt/β-catenin signal transduction pathway, indicating that TIMP2 contributes to the pathogenesis and progression of melanoma." (PMID 32934956, 2020). "TIMP2 was shown to reduce the tube formation ability of the murine melanoma cell line B1624." (PMID 31591386, 2019). "Our data indicate that loss of CYLD contributes to angiogenesis in melanoma by a potential negative effect on expression of several anti-angiogenic factors like TIMP-2, TIMP-3 and ADAMTS5." (PMID 31591386, 2019). "Finally, miR-4443 was also reported to target the tissue inhibitor of metalloproteinase 2 (TIMP2) which is involved in Vemurafenib resistance increasing melanoma invasiveness." (PMID 30254376, 2019). "Therefore we also studied the efficiency of APs to deliver TIMP2 gene to mouse melanoma cell line B16-F10 and to B16-F10 tumors in mice." (PMID 27088717, 2016). "In addition, TIMP-2 promotes cell growth by activating nuclear factor kappa B (NF-κB) in A549 cells and melanoma cells." (PMID 26556867, 2015). "In addition to collagenases-1 and -3 that have been implicated in invasive growth behaviour of various malignant tumours, we analysed the levels of 72-kDa gelatinase and its activators MT1-MMP and TIMP-2 in cultured melanoma cells." (PMID 10360651, 1999). "Local overexpression of TIMP2 in tumor tissue may provide anti-tumor activity in melanomas." (PMID 36816748, 2023). "Hence, we assessed TIMP2 expression levels upon miR-4443 overexpression in M14S melanoma cells." (PMID 30254376, 2019). "Studies show that the expression of Timp2 (tissue inhibitor of metalloproteinase 2), Timp3 (tissue inhibitor of metalloproteinase 3) and Adamts5 (a disintegrin-like and metalloproteinase with thrombospondin type 1 motif, 5) reduce angiogenesis in melanoma cells." (PMID 31591386, 2019). "Exposure to melanoma-conditioned medium induced the upregulation of bFGF, CXCL-16, TIMP-2, and E-cadherin in NHKs, alongside downregulating TGF-β and MMP-9." (PMID 40869222, 2025).